TERT (telomerase reverse transcriptase)
Diseases named in the same sentence as TERT in open-access papers (continued):
Sharing a sentence is not in itself a finding about the gene and the disease.
cancer (continued). "Following the identification of TERT promoter mutations in cancer, several authors have screened other promoter regions searching for mutations that can be relevant in cancer." (PMID 28662141, 2017). "Although these studies have focused on the associations between TERT SNP and some type cancer diseases, however, few study focused on the relationship between TERT SNP and GC risk." (PMID 28423629, 2017). "Recently, two somatic hotspot mutations were discovered in the TERT promoter that specifically occurred in a subset of cancers." (PMID 28184371, 2017). "We calculated FPRP values for associations between the TERT rs2736100 T>G polymorphism and overall cancer risk using the five genetic models." (PMID 28418878, 2017). "Increased telomerase activity is perceived to be one of the hallmarks of human cancers, and the transcriptional regulation of the TERT gene is the major cause of its cancer-specific activation." (PMID 29165358, 2017). "The TERT gene sequence in general is thought to be indicative of an individual’s susceptibility to cancer, and epidemiological studies have identified associations between specific TERT polymorphisms and cancer development." (PMID 28060765, 2017). "It has been reported that the rs2242652 allele of TERT influences telomere length, which was associated with risk of several cancers." (PMID 29299136, 2017). "Non-coding mutations such as TERT promoter mutations have been associated with clinical outcomes, as have mutational processes in cancer." (PMID 28056774, 2017). "TERT upregulation or reactivation seems to be associated with several “hallmarks of cancer” including increased mitochondrial activity, DDR signaling, and WNT/β-catenin signaling." (PMID 28218725, 2017). "Normally, TERT mRNA is not expressed in most human somatic cells; however, aberrant expression of TERT mRNA and protein are associated with development of various cancers." (PMID 29221218, 2017). "Our findings represent the first steps in unravelling the complex functional consequences of carrying risk variants in Region 2 of chr5p15.33 and strongly indicate a major role for expression of TERT in influencing risk of multiple cancer types." (PMID 28447668, 2017). "The first identified non-coding driver element was the TERT promoter with highly recurrent mutations across several cancer types." (PMID 28362259, 2017). "CLPTM1L, near the TERT gene, is located at chromosome 5p15.33 which is widely identified as a susceptibility region associated with several types of cancer." (PMID 29254260, 2017). "First, there were substantial heterogeneities in the pooled study investigating the association between the TERT rs2736100 polymorphism and overall cancer risk." (PMID 28418878, 2017). "Investigations on cancer-specific TERT promoter mutations help us to understand the mechanistic basis of the activation of the dormant TERT promoter in cancers." (PMID 28272339, 2017). "For rs2736100, the cancer risk genotype CC was significantly associated with a reduced incidence of TERT promoter mutations compared to AA + AC variants [Odds ratio (OR): 0.181, 95% Confidence interval (CI): 0.0543–0.601, P = 0.004]." (PMID 28416747, 2017). "The frequencies of TERT mutations in HCC have shown to vary by cancer etiology and geographic patient provenance." (PMID 28529542, 2017). "As several new studies have been updated since the latest meta-analysis, it is necessary for us to incorporate all the accessible studies to better elucidate the association between TERT rs2736098 polymorphism and cancer risk." (PMID 29221218, 2017). "We also detected mutations in the core promoter of the TERT gene, which have been reported in different cancers including skin." (PMID 28410231, 2017). "Our results also associated the TERT rs2736100 polymorphism with elevated overall cancer risk in all subgroups divided by sample size of controls and quality score in all the five genetic models." (PMID 28418878, 2017).
cancer (continued). "We then adopted odds ratios (ORs) and 95% confidence intervals (CIs) to analyze the contributions of TERT rs2736098 to cancer risk." (PMID 29221218, 2017). "We also used a PCR-based assay followed by next generation sequencing to evaluate the presence and cancer cell fraction of the TERT promoter mutation." (PMID 29872714, 2017). "Here, we conducted this updated meta-analysis, aiming to comprehensively evaluate the role of TERT rs2736098 in cancer risk." (PMID 29221218, 2017). "Mutations in the TERT promoter represent the most common non-coding somatic mutations in cancer and it would be interesting to investigate the role of Myc in regulating the mutant TERT promoter." (PMID 28184371, 2017). "The rs2736100 T > G polymorphism in the telomerase reverse transcriptase (TERT) gene, which encodes the telomerase catalytic subunit, has been associated with increased cancer risk." (PMID 28418878, 2017). "This review discusses the cancer-specific TERT promoter mutations and potential biological and clinical significances." (PMID 27438857, 2016). "Affinity changes can be directly associated with cancer progression with a striking example of a GABP (ETS-family factor) binding site emerging in TERT promoter associated with progression of different tumors." (PMID 27356864, 2016). "The mechanism of telomerase re-activation in cancer had remained elusive until the discovery of frequent mutations in the promoter of the TERT gene that encodes the catalytic reverse transcriptase subunit of telomerase." (PMID 27449293, 2016). "In the light of these findings and considering the close correlation of TERT gene expression and telomerase activity with cancer, investigations focused on deciphering the underlying mechanisms that govern TERT promoter activity." (PMID 27483324, 2016). "Taken together, the TERT promoter mutation enhances high TERT expression, thereby contributing to aggressive phenotypes of cancer cells and poor patient outcomes via both telomere lengthening-dependent and independent mechanisms." (PMID 27438857, 2016). "Given TERTs critical role in carcinogenesis, SNPs at the TERT locus have been extensively analyzed for their association with cancer risk, among which rs2736100 variants are most studied." (PMID 27561898, 2016). "Very recently, two prevalent and mutually exclusive mutations in the promoter of TERT (228C>T and 250C>T) emerged as the most frequently observed non-coding mutations in cancer and were associated with high levels of telomerase in multiple cancer types." (PMID 27501725, 2016). "Given that TERT promoter mutations have been widely found in diverse cancers, these mutations are likely to be one of the mechanisms of telomerase activation in this cancer." (PMID 26556853, 2016). "Since BC and renal pelvic cancer (RPC) exhibits a high frequency of TERT promoter mutations, the test for them as cancer biomarkers has been predominantly performed on these two malignancies." (PMID 27438857, 2016). "Binding sites of GABP, a member of ETS family, are created by mutations in TERT promoter and associated with development of many cancer types." (PMID 27356864, 2016). "A common single-nucleotide polymorphism in the telomerase reverse transcriptase (TERT) promoter, rs2853669 influences patient survival rates and the risk of developing cancer." (PMID 26575952, 2016). "TERT promoter mutations have been found in many human cancers, including melanomas, bladder carcinomas, and thyroid carcinomas." (PMID 27056898, 2016). "Subsequent studies showed occurrence of somatic TERT promoter mutations in a wide range of cancer types." (PMID 27449293, 2016). "The discovery of activating somatic mutations within the core promoter region of the TERT gene has provided an insight into the possible cause of telomerase re-expression in some cancer types." (PMID 27449293, 2016).
cancer (continued). "Recently, hotspot point mutations in the regulatory region of the telomerase reverse transcriptase (TERT) gene, encoding the core catalytic component of telomerase, was identified as a novel mechanism to activate telomerase in cancer." (PMID 27438857, 2016). "Cancer risk is associated with common single-nucleotide polymorphisms (SNPs), including the TERT gene variant, rs2853669 (−245T > C)." (PMID 26575952, 2016). "Second, a sgRNA against the newly synthesized NHEJ-derived junction was coelectroporated with Donor plasmids containing the deleted region with cancer-associated TERT promoter mutations." (PMID 27403431, 2016). "The identification of TERT promoter mutations has led to several systematic searches of non-coding somatic mutations across various cancers." (PMID 27611953, 2016). "In recent years, the mechanism underlying TERT transcriptional activation in cancer cells has been an active area of investigation." (PMID 27833153, 2016). "Approximately 90% of all human cancers contain an increased level of telomerase, and understanding the epigenetic regulation of the gene that encodes for the TERT subunit provides a mechanism for controlling its expression." (PMID 27242892, 2016). "Recently, several lines of evidence suggest that the rs2853669 suppresses TERT promoter mutation-mediated TERT expression levels and cancer mortality as well as recurrence rates." (PMID 26575952, 2016). "Direct evaluation of the TERT promoter mutation as a prognostic factor has been made in many types of cancer." (PMID 27438857, 2016). "Single nucleotide polymorphisms (SNPs) in the TERT-CLPTM1L locus on chromosome 5p15.33 have been linked to a spectrum of cancers." (PMID 26621837, 2016). "Since rs2736100 G allele is associated with elevated TERT expression, the associations between the polymorphism and increased cancer risk are biologically plausible." (PMID 26716642, 2016). "Increased applications of the TERT promoter mutation as biomarkers for cancer diagnostics and disease surveillance will be expected in near future." (PMID 27438857, 2016). "During last three years, the TERT promoter mutations have been widely investigated and identified in various types of human cancer with different frequencies." (PMID 27438857, 2016). "TERT’s extra-telomeric functions are implicated in regulating several cancer hallmarks including cell proliferation, angiogenesis, invasion, and metastasis." (PMID 27501725, 2016). "More recently, Indian patients with cervical cancer were shown to have a high rate of TERT promoter mutations in their tumors, in striking contrast to their rarity in this cancer type from other countries." (PMID 27438857, 2016). "Recently, the relationship between genetic variants in TERT and the etiology of cancers has drawn increasing attention." (PMID 26857734, 2016). "The presence of TERT promoter mutations in human malignancies whereas their absence in normal tissues/cells provides new cancer-specific markers." (PMID 27438857, 2016). "Variants that confer risk of some cancers and protect against others have been observed before, for example in the TERT-CLPTM1L locus." (PMID 26740556, 2016). "Recently, hotspot TERT promoter mutations were identified to stimulate the TERT transcription or telomerase activation and to occur in various types of cancer." (PMID 27438857, 2016).
cancer (continued). "TERT has been proposed to regulate miRNAs by regulation of miRNA biogenesis, with diminished primary miRNA expression in TERT-reduced cells, and has been shown to be associated with both TL and cancer." (PMID 27627813, 2016). "We also observed that genetic variation in TERT, which we have previously reported as being associated with TL and cancer, was associated with miRNA expression levels." (PMID 27627813, 2016). "In cancer cells carrying heterozygous TERT promoter mutations, the mutant promoter recruits the GABPA transcription factor and exhibits the H3K4me2/3 mark of active chromatin." (PMID 27438857, 2016). "TERT promoter mutations appear to correlate with increased TERT expression and telomerase activity in these cancers." (PMID 27792139, 2016). "Highly recurrent mutations in the TERT promoter were found in over 50 cancer types and are the most common mutations in many cancers, making telomerase activation an attractive target for cancer therapy." (PMID 27537914, 2016). "TERT promoter mutations are one of the most frequent somatic alterations in a variety of human cancers." (PMID 27056898, 2016). "The rs2736100 is located at intron 2 of the TERT locus, and its CC genotype was previously observed to enhance TERT transcription, thereby increasing cancer risk." (PMID 27561898, 2016). "Evaluation of differences in miRNA expression levels between carcinoma tissue and normal colorectal mucosa showed that TERT rs2736118 was associated with differential miRNA expression based on genotype." (PMID 27627813, 2016). "TERT rs2736118 was associated with differences in miRNA expression between carcinoma and normal colonic mucosa for 75 miRNAs (FDR <0.05)." (PMID 27627813, 2016). "It is well established that cancer cells have high telomerase activity levels, but few coding mutations have been identified within the TERT gene." (PMID 26356674, 2015). "To date, only in ChRCC cases have promoter SVs been thus far identified, and a survey of other cancer types for structural variants impacting TERT remains to be carried out." (PMID 25859550, 2015). "We performed a meta-analysis to summarize the available evidence and more precisely characterize the relationship between the TERT rs2853676 polymorphism and cancer risk." (PMID 26042809, 2015). "We aimed to understand the molecular basis by which the cancer-associated TERT mutations impact telomerase biology." (PMID 26194807, 2015). "Previous studies that evaluated the effects of TERT promoter mutations on TERT expression levels and telomerase activity in cancer cell lines had found relatively modest differences between mutant and wild type cells." (PMID 26194808, 2015). "Using genome editing of the endogenous TERT locus we generated a panel of three hESC lines that differed exclusively at a single position in the TERT promoter associated with cancer." (PMID 26194807, 2015). "Only one falls into a haplotype previously associated with other cancer types (rs7705526, in TERT intron 1), and this SNP has been shown to alter TERT promoter activity." (PMID 25487306, 2015). "Our meta-analysis suggested that the TERT genetic polymorphism rs2853676 allele A increased several cancer risk, based on 76 108 cases and 134 215 controls." (PMID 26042809, 2015). "We tested several sgRNAs in proximity to TERT promoter mutations and found them to be toxic to cells shortly after transfection into cancer cells and human primary fibroblasts." (PMID 26194807, 2015). "TERT encodes an enzyme, telomerase, whose increased activity is associated with malignant tumors due to its role in proliferation and apoptosis of cancer cells and has been found to be active in 90% of human cancers." (PMID 26431041, 2015). "The clinical significance of these findings is highlighted by the current investigation of TERT promoter mutations as potential biomarkers for cancer prognosis." (PMID 26356674, 2015).
cancer (continued). "In summary, we provide the first evidence that a well-documented cancer risk-associated polymorphism in the TERT-CLPTM1L locus encodes an alternative splice variant of hTERT, which results in a catalytically inactive telomerase enzyme complex." (PMID 26053551, 2015). "For the cancers surveyed here, TERT promoter mutations were mainly found within bladder cancers and glioblastomas, as well as for three of our ChRCC cases." (PMID 25859550, 2015). "While TERT promoter mutations independently associate with poor in survival in many cancers, the mutations also associate with reduced telomere length." (PMID 25797251, 2015). "We conducted a search in PubMed, Google Scholar and ISI Web of Science to select studies on the association between TERT rs2853676 and cancer risk." (PMID 26042809, 2015). "WS shares some common features with other telomere diseases, most represented by mutation of telomerase complex (TERC and TERT), like skin hyperpigmentation, premature hair greying, myeloid disorder, and risk of cancer." (PMID 26788395, 2015). "Non-coding mutations in the promoter of the catalytic subunit of telomerase (TERT) emerged recently as one of the most prevalent mutations in human cancer." (PMID 26194807, 2015). "Several studies have suggested that TERT promoter mutations can provide a biomarker to stratify human cancer subtypes." (PMID 26194807, 2015). "Many molecular epidemiology studies have demonstrated genetic variations in the TERT gene as risk factors for many cancer types." (PMID 26020272, 2015). "Under these conditions all cancer-associated TERT mutations prevent repression of TERT, resulting in a retention of telomerase activity relative to wild-type differentiated cells." (PMID 26194807, 2015). "A significant association between TERT rs2853676 allele A and cancer susceptibility was demonstrated under a per-allele risk analysis (OR = 1.08, 95% CI = 1.04-1.13)." (PMID 26042809, 2015). "Another set of experiments introduced single base-pair changes in the TERT gene promoter at sites of recurrent cancer-specific mutations, which had previously been found to be associated with increased telomerase activity." (PMID 26553065, 2015). "We selected four TERT SNVs on the basis of previous reports of their association with the risk for several other forms and hallmarks of cancer and its potential as a biomarker of clinical outcome in AML." (PMID 26298771, 2015). "The TERT-CLPTM1L region of chromosome 5p15.33 is a multi-cancer susceptibility locus that encodes the reverse transcriptase subunit, hTERT, of the telomerase enzyme." (PMID 26053551, 2015). "Chr5p15.33 harbors a unique cancer susceptibility region that contains at least two plausible candidate genes: TERT and CLTPM1L." (PMID 26372813, 2015). "In contrast, fibroblasts with the cancer-associated promoter mutations showed high levels of TERT expression." (PMID 26194807, 2015). "The TERT gene sequence has been proposed as a general mechanism affecting individual susceptibility to cancer risk." (PMID 26042809, 2015). "Nonetheless, much remains to be learned about the role of TERT promoter mutations in the formation of cancer." (PMID 26194808, 2015). "TERT promoter mutations have been identified in 6 of 14 cancer types where they occur in 3 to 62% of cancer samples, depending on the type of cancer." (PMID 26562774, 2015). "This complementation strategy therefore successfully generated hESCs that differed exclusively at the TERT locus by expressing TERT either from its wild-type promoter or from a promoter that contained one of the cancer-associated point mutations." (PMID 26194807, 2015). "The prevalence of TERT promoter mutations, their intuitively obvious importance for cancer development and progression, and the resulting therapeutic potential, will undoubtedly unleash significant efforts to answer these questions in the near future." (PMID 26194808, 2015).